SHOX2 (SHOX homeobox 2)
Diseases named in the same sentence as SHOX2 in open-access papers (continued):
Sharing a sentence is not in itself a finding about the gene and the disease.
cancer (continued). "Hypermethylation of the SHOX2 and SEPT9 gene loci in ccfDNA has been known as valuable diagnostic and prognostic tests for patients suffering from HNSCC and other cancers." (PMID 29213339, 2017). "The cellular fraction of cancer patients was positive for SHOX2 and SEPT9 in 11 and 18 %, respectively." (PMID 26937257, 2016). "Since high methylation values of SHOX2 did not correlate significantly with SEPT9 hypermethylation (Pearson’s correlation coefficient r = 0.24, p value = 0.08), the combined panel was expected to detect more cancer specimens than SHOX2 or SEPT9 alone." (PMID 27999621, 2016). "In this study, both biomarkers showed a specificity of 98 to 99 % while positivity of SHOX2 or SEPT9 DNA methylation in cancer patients was rather low ranging from 11 to 23 %." (PMID 26937257, 2016). "Cancer patients positive for SHOX2 or SEPT9 cellular DNA methylation have a significantly worse prognosis." (PMID 26937257, 2016). "SHOX2 DNA methylation was significantly higher in plasma specimens from CC patients than from controls and correctly identified 35% (7/20) of carcinoma cases." (PMID 27999621, 2016). "In the next sections we will provide an overview of SHOX2, PITX2 and MGMT as good examples of diagnostic, prognostic and predictive biomarkers in cancer." (PMID 25229548, 2014). "Recently, SHOX2 DNA methylation was shown to be a useful biomarker for detecting cancer patients at high specificity and sensitivity in a group of critical controls based on the analysis of bronchial lavage samples." (PMID 21426551, 2011). "The expression of SHOX2 is significantly elevated in the majority of cancer types." (PMID 38840077, 2024). "Analyses found that SHOX2 was overexpressed in multiple cancer types." (PMID 37170390, 2023). "SHOX2 and RASSF1A methylation has been associated with high expression of Ki-67, which may indicate that cancer cells are proliferating." (PMID 37182143, 2023). "Thus, comprehensive bioinformatics analyses of pan-cancer datasets were conducted to explore how SHOX2 regulates tumorigenesis." (PMID 37170390, 2023). "SHOX2 was overexpressed in multiple cancer types in TCGA cohort." (PMID 37170390, 2023). "In this research, we investigated the biological functions of SHOX2 in a variety of cancers." (PMID 37170390, 2023). "Many studies have reported that SHOX2 is highly expressed in many cancers." (PMID 34262939, 2021). "To explain the discrepancy of high methylation of SHOX2 in cancer tissue and to identify whether methylation occurs at the gene promoter, we conducted further research to try to explain this phenomenon." (PMID 34262939, 2021). "Some TSGs, including GSTP1, MGMT, CDH1, P16, RAR-β2, septin 9 (SEPT9), syndecan 2 (SDC2), cyclin-dependent kinase inhibitor 2A (CDKN2A), and short stature homeobox 2 (SHOX2), have been validated to be silenced through DNA methylation in various types of cancer." (PMID 32075099, 2020). "Based on SHOX2 methylation level in cancer specimens, the results were organized in three groups." (PMID 33425721, 2020). "SEPT9 and SHOX2 both have been shown to be strong and valid biomarkers in several cancer entities." (PMID 29213339, 2017). "Although these promising findings in other cancer entities suggested that aberrant SHOX2 and SEPT9 methylation may also correlate with prognosis in BTC, our results did not confirm this hypothesis." (PMID 27999621, 2016). "Therefore, a Kaplan-Meier survival analysis of the cancer patients stratified by the SHOX2 and SEPT9 methylation levels was conducted." (PMID 24386354, 2013). "Furthermore, DNA methylation analysis in PEs allowed the prognosis of the overall survival in cancer patients (Kaplan-Meier analysis, log rank test, p = 0.02 (SHOX2), p = 0.02 (SEPT9))." (PMID 24386354, 2013). "In addition, SHOX2 affected the sensitivity of cancer patients to immunotherapy was next assessed." (PMID 37170390, 2023). "Additionally, the SHOX2 methylation status showed promising results in other cancer types." (PMID 27660666, 2016).
cancer (continued). "Comparison of the expression of SHOX2, RASSF1A, and PTGER4 in cancer tissues and paracancerous tissues of LC patients (n (%))." (PMID 40386526, 2025). "The methylation positive rates of SHOX2, RASSF1A and PTGER4 genes in cancer tissues were 48.00%, 32.00% and 64.00%, significantly higher than those in para-carcinoma tissues (16.00%, 4.0%, 14.00%, P<0.05)." (PMID 40386526, 2025). "The positive expression rates of SHOX2, RASSF1A and PTGER4 in cancer tissues were 44.0%, 54.00% and 50.00%, significantly lower than those in para-carcinoma tissues (90.00%, 96.00%, 82.00%, P<0.05)." (PMID 40386526, 2025). "By using the optimal methylation cutoff value for individual genes, the positive detection rates of each marker in malignant tumor patients ranked from high to low were 46.3% (HOXA9), 45.1% (SHOX2), 31.1% (SEPTIN9) and 18.9% (RASSF1A)." (PMID 41477641, 2025). "Comparison of the positivity rates of detecting SHOX2, RASSF1A, and PTGER4 gene methylation in cancer tissues and paracancerous tissues of LC patients (n (%))." (PMID 40386526, 2025). "The positive expression rates of SHOX2, RASSF1A and PTGER4, and positive rates of SHOX2, RASSF1A and PTGER4 genes methylation in cancer tissues and para-carcinoma tissues were compared." (PMID 40386526, 2025). "Our findings with the OncoMe panel (SHOX2, RASSF1A, SEPTIN9, and HOXA9) in malignant ascites are consistent with and extend previous reports on DNA methylation biomarkers in body fluids." (PMID 41477641, 2025). "Two extensively studied biomarkers, short stature homeobox 2 (SHOX2) and Septin 9 (SEPT9), have been investigated in various cancer types." (PMID 38339235, 2024). "Based on the cutoff values, the positive rate of SHOX2 and RASSF1A methylation were 50.7% (105/207) and 45.4% (94/207) in cancer group." (PMID 38840077, 2024). "Several have been proposed for the detection of PDAC or other cancers in blood, including BCAN, IKZF1, TBX15, BNC1 and SHOX2." (PMID 36434648, 2022). "The biomarkers short stature homeobox 2 (SHOX2) and Septin 9 (SEPT9) are well characterized in patients with different cancer entities." (PMID 36139516, 2022). "Although, the functions of SHOX2 and RASSF1A in some cancer contexts have been reported, the role of SHOX2 and RASSF1A in the occurrence and development of LUAD remain to be explored." (PMID 35837113, 2022). "SHOX2 is involved in PI3K−Akt and other important cancer-related signaling pathways to promote tumorigenesis." (PMID 34262939, 2021). "Comparison of the methylation levels of SHOX2 and RASSF1A between cancer and cancer-adjacent specimens (n = 30), showed they have “epigenetic field defect”." (PMID 33425721, 2020). "Next, the methylation levels of SHOX2 and RASSF1A in 30 pairs of cancer and caner-adjacent tissues were analyzed." (PMID 33425721, 2020). "In most of the cases (group 2), the significant reduction in the methylation level of SHOX2 and/or RASSF1A between cancer and cancer-adjacent specimen was observed." (PMID 33425721, 2020). "In the training group, the methylation levels of SHOX2 and PTGER4 in cancer patients were significantly higher than those in healthy controls (p < 0.05)." (PMID 31888670, 2019). "Our and other groups established differential methylation-specific qPCR assays of the stature homeobox 2 (SHOX2) and septin 9 (SEPT9) in various cancer entities with possible biomarker properties for early detection and response prediction strategies." (PMID 27660666, 2016). "A similar fraction of cancer samples showed high methylation in each gene (2/20 for HIST1H3J, 8/20 for POU4F2, 4/20 for SHOX2, 5/20 for PHKG2, 6/20 for TLX3, and 4/20 for HOXA7)." (PMID 24367375, 2013). "Out of 58 cancer patient samples, 12 (21%) showed detectable SEPT9 methylation and seven (12%) showed SHOX2 DNA methylation levels above the cut-off and were defined as methylation positive." (PMID 24386354, 2013).
cancer (continued). "The positive expression rates of SHOX2, RASSF1A, and PTGER4 in cancer tissues of LC patients were 44.0%, 54.00%, and 50.00%, respectively, which were significantly lower than those in paracancerous tissues, which were 90.00%, 96.00%, and 82.00%, respectively (P < 0.05)." (PMID 40386526, 2025). "The methylation positivity rates of SHOX2, RASSF1A, and PTGER4 genes in cancer tissues of LC patients were 48.00%, 32.00%, and 64.00%, respectively, which were significantly higher than those in paracancerous tissues, which were 16.00%, 4.0%, and 14.00%, respectively (P < 0.05)." (PMID 40386526, 2025). "In conclusion, we found that the aberrant promotor methylation of OncoMe (SHOX2, RASSF1A, SEPTIN9 and HOXA9) was a cancer-specific alteration and might be a valuable marker to aid in the differentiation of MA." (PMID 41477641, 2025). "The results of this study showed that the positive expression rates of SHOX2, RASSF1A and PTGER4 in cancer tissues of LC patients were significantly lower than that in paracancerous tissues, suggesting that low expression of SHOX2, RASSF1A and PTGER4 is common in LC patients." (PMID 40386526, 2025). "Several studies have concentrated on the detection of aberrant methylation of the SHOX2 and RASSF1A genes in plasma cfDNA as well as bronchoalveolar lavage fluid specimens to help improve the diagnosis of malignant tumors, while little attention has been given to cfDNA methylation in PE." (PMID 36691467, 2023). "These DMRs were enriched for regulatory regions of well-known cancer-related gene families such as PAX family genes, TBX family genes, FOX family genes, and HOX family genes, and some have previously been reported as biomarkers for non-invasive cancer diagnosis, such as SEPT9 and SHOX2." (PMID 37819044, 2023). "Furthermore, hypermethylated SHOX2- and SEPT9- (mSHOX2 and mSEPT9) genes in ccfDNA were proclaimed as conclusive and powerful pan-cancer biomarkers." (PMID 36139516, 2022). "SHOX2 could be involved in PI3K–Akt and other important cancer-related signaling pathways to promote tumorigenesis." (PMID 34262939, 2021). "Our observation indicated that SHOX2 and RASSF1A may play different roles in the process of cancer development." (PMID 33425721, 2020). "Our observation indicated that SHOX2 and RASSF1A might play different roles in initiation, proliferation, invasion, and metastasis of cancer development." (PMID 33425721, 2020). "Our observation revealed that SHOX2 and RASSF1A may play different roles in initiation, proliferation, invasion, and metastasis of cancer development." (PMID 33425721, 2020). "SHOX2 and SEPT9 methylation in circulating cell-free DNA (ccfDNA) in blood are established powerful and clinically valuable biomarkers for diagnosis, staging, prognosis, and monitoring of cancer patients." (PMID 29213339, 2017). "The diagnostic benefit in addition to the prognostic value of DNA methylation in cancer and non-cancer patients indicates that SHOX2 and SEPT9 methylation is a biomarker for an advanced malignancy." (PMID 26937257, 2016). "Therefore, a targeted sequencing should be performed in further studies in order to clarify the methylation status of SHOX2 and SEPT9 in cancer." (PMID 27999621, 2016). "All the genes except SHOX2 showed no or very low expression in the analyzed, methylated cancer cell line, and showed re-expression in cells treated with 5-aza-2′-deoxycytidine and/or trichostatin A." (PMID 24367375, 2013). "Nonetheless, the biological role of SHOX2 within pan-cancer datasets has not been investigated." (PMID 37170390, 2023). "Interestingly, Hsia and colleagues demonstrated that SHOX-2 expression is high to moderate in skin fibroblasts or activated fibroblasts respectively, but almost absent from myofibroblasts in cancer and normal tissues." (PMID 35935486, 2022). "However, the comprehensive researches of SHOX2 in various cancers has not been studied at present." (PMID 37170390, 2023).
cancer (continued). "Later, the analysis of a combination of SHOX2 and PTEGR4 methylation levels in blood demonstrated significant discriminatory performance in distinguishing patients with LC from subjects without malignancy (AUC = from 0.86)." (PMID 36123616, 2022). "SHOX2 and SEPT9 were hypermethylated in the cellular fraction (n = 283, p = 0.001, p < 0.052, respectively) and cfDNA (n = 162, p = 0.001, p < 0.001) in the ascitic fluid of cancer patients compared to patients with non-malignant diseases." (PMID 26937257, 2016).
adenocarcinoma (10 papers, 2010 to 2026). A common cancer characterized by the presence of malignant glandular cells. "In our cohort, MPE was principally adenocarcinoma-derived, and whether the methylation positive rates of SHOX2 and RASSF1A are different in specific disease subtypes needs further exploration." (PMID 36691467, 2023). "In terms of different pathological types and TNM staging, methylation positive rates of SHOX2 and RASSF1A genes were the highest in patients with adenocarcinoma and TNM staging at stage IV." (PMID 40386526, 2025). "Based on FFPE samples, the positive detection rates of the SHOX2 and RASSF1A panels in SCLC, SCC, and adenocarcinomas were 100%, 96.1%, and 82.9%, respectively." (PMID 36691467, 2023).
heart disease (2 papers, 2013 to 2019). "Another relevant gene is SHOX2 (3q25.32), a member of the homeobox family which is one of the major genes involved in the development of the sinoatrial node; its proper function is of crucial relevance for the origin of arrhythmogenic heart disease." (PMID 31480262, 2019).
SHOX2 also shares sentences with these, for which no sentence is quoted: genetic disorders (3 papers); mesothelioma (3); cardiac arrhythmias (2); colon cancer (2); head and neck cancer (2); Léri-Weill dyschondrosteosis (2); lung neoplasm (2); oral squamous cell carcinoma (2); pancreatic cancer (2); sarcoma (2); testicular germ cell tumor (2); wasting syndrome (2); adenopathy (1); age (1); amebiasis (1); anaplastic glioma (1); benign tumors (1); bile duct cancer (1); bladder cancers (1); breast invasive carcinoma (1); cardiomyopathies (1); cervical squamous cell carcinoma (1); colonic adenomas (1); colorectal adenocarcinoma (1); Cornelia de Lange syndrome (1); endometrioid adenocarcinoma (1); esophageal carcinoma (1); esophagus cancer (1); Hutchinson-Gilford progeria syndrome (1); ischemia (1).
A further 18 diseases each share a sentence with SHOX2 in 1 paper.